LYPD4 (LY6/PLAUR domain containing 4)
Synonyms: MGC42718; SMR
Tractability: Antibody: UniProt places it where antibodies can reach, with high confidence; its Gene Ontology location is reachable by antibodies, with high confidence; UniProt predicts a signal peptide or a membrane-spanning region.
Gene: Protein-coding gene on chromosome 19 (41,837,074 to 41,844,697, reverse strand). Ensembl gene ENSG00000273111.
Subcellular location: Cell membrane
Pathways (Reactome):
Metabolism of proteins: Post-translational modification: synthesis of GPI-anchored proteins
Gene Ontology:
Cellular component: extracellular region; plasma membrane; plasma membrane raft; acrosomal vesicle
Genetic constraint (gnomAD): Loss-of-function variants: 21 observed, 20.14 expected, observed/expected ratio (o/e) 1.04, 90% interval 0.74 to 1.5. The upper end of that interval is the gene's LOEUF score, 1.5, which puts it in group 6 of 6, group 1 being the genes least tolerant of losing a copy. Missense variants: 278 observed, 309.86 expected, observed/expected ratio (o/e) 0.9, 90% interval 0.81 to 0.99. Synonymous variants: 111 observed, 122.9 expected, observed/expected ratio (o/e) 0.9, 90% interval 0.77 to 1.06.
Homologues: Orthologues: chimpanzee LYPD4 (99% identical), macaque LYPD4 (96% identical), dog LYPD4 (77% identical), pig LYPD4 (73% identical), mouse Lypd4 (70% identical), rat Lypd4 (69% identical), guinea pig LYPD4 (66% identical). Paralogues in human: CD177 (30% identical), TEX101 (25% identical).
Diseases named in the same sentence as LYPD4 in open-access papers:
LYPD4 is named in the same sentence as 20 diseases in open-access papers, as found by Europe PMC text mining. Sharing a sentence is not in itself a finding about the gene and the disease. The quoted sentences say what the papers report.
Infertility (1 paper, 2019). "Our findings support a potential role of human LYPD4 in sperm function and could be used to develop infertility treatments as well as male-specific contraceptives." (PMID 31455729, 2019). "To analyze the infertility of Lypd4 KO males, we performed IVF assays using Cau Epi spermatozoa from Lypd4 KO males mixed with cumulus-intact oocytes." (PMID 31455729, 2019).
male infertility (1 paper, 2019). The inability of the male to effect fertilization of an ovum after a specified period of unprotected intercourse. "Further experiments may be required to examine the cause of male infertility in Lypd4 KO mice and how sperm acrosomal membrane protein LYPD4 is affected to gain sperm fertilizing ability." (PMID 31455729, 2019). "Male infertility of Lypd4 KO mice may be caused by abnormalities in sperm protein(s) other than ADAM3." (PMID 31455729, 2019).
LYPD4 also shares sentences with these, for which no sentence is quoted: portal hypertension (7 papers); Cirrhosis (6); infection (4); Sepsis (3); Hepatic fibrosis (2); alcoholic liver diseases (1); asthma (1); bacterial infections (1); cancer (1); COVID-19 (1); endotoxemia (1); fibrosis (1); fungal infections (1); Insulin resistance (1); liver cirrhosis (1); Obesity (1); pneumonia (1); Wilson disease (1).